IL17A (interleukin 17A)
Diseases named in the same sentence as IL17A in open-access papers (continued):
Sharing a sentence is not in itself a finding about the gene and the disease.
Psoriasiform dermatitis (31 papers, 2013 to 2025). A skin abnormality characterized by redness and irritation, with thick, red skin that displays flaky, silver-white patches (scales). "Oral administration of deoxycholic acid significantly improved psoriasiform dermatitis in murine model, potentially by inhibiting IL-17A production and blocking CCL20-mediated trafficking." (PMID 39850616, 2025). "Mice with systemic and conditional depletion of PELI1 were protected from psoriasiform dermatitis and showed reduced IL-17A production and NFkB activation in Th17 cells." (PMID 36901778, 2023). "The inhibition of PELI1 significantly ameliorated murine psoriasiform dermatitis by reducing IL-17A production." (PMID 36901778, 2023). "In this study, we established a mouse model of psoriasiform dermatitis by intradermal IL-17A injection in STAT3 overexpressing mice." (PMID 37465147, 2023). "Further studies using in vivo models for psoriasiform dermatitis or other IL-17 driven disease are warranted to comprehensively investigate the cellular source of IL-17A." (PMID 35401573, 2022). "IL-17A-/- and IL-23-/- mice showed the same phenotype, suggesting that IL-36 cytokines contribute to the severity of experimental psoriasiform dermatitis by inducing the expression of IL-23 and IL-17A." (PMID 34887860, 2021). "In terms of mechanism, mice in P group with increased IL-17A expression in the gastrointestinal tissue correspondingly showed delayed reduction of IL-17A in lesions and delayed recovery of psoriasiform dermatitis." (PMID 34881280, 2021). "The short-time (4 weeks) feeding with Western diet promoted the accumulation of IL-17A-producing γδT cells with enriched IL-23 receptor expression in IMQ-induced psoriasiform dermatitis." (PMID 32751360, 2020). "Stimulation of TP in γδT17 cells enhanced IL-23-induced production of IL-17A while inhibitors of TXA2 synthase ameliorated the IMQ-induced psoriasiform dermatitis and suppressed the IL-17 production by γδT17 cells." (PMID 32751360, 2020). "Resolvin D1 alleviated the IMQ-induced psoriasiform dermatitis and reduced the expression of IL-23, IL-17A, IL-17F, IL-22, and TNF-α in the lesions." (PMID 32751360, 2020). "The IL17 family is composed of 6 members IL17A to F. To this day, the leukocyte-derived IL17A/F interleukins were the most studied and were described as the most important player in psoriasiform dermatitis." (PMID 27050272, 2016). "Moreover, the vitamin D analog, Maxacalcitol, significantly inhibits IMQ-induced psoriasiform dermatitis and reduces IL-17A mRNA expression in the skin, while also increasing Foxp3+ Treg cells." (PMID 37818377, 2023). "To assess the impact of CD103 on the regulation of the axis of IL-22-IL-23-IL-17 cytokine, we compared the induction of IL-17A- and IL-22-producing lymphocytes in the skin-draining PLNs between WT mice and Cd103−/− mice following initiation of psoriasiform dermatitis." (PMID 32433498, 2020). "BAs can directly inhibit IL-17A production and block CCL20-mediated transport to ameliorate psoriasiform dermatitis with minimal toxicity." (PMID 38482003, 2024). "Psoriasiform dermatitis model was established by imiquimod (IMQ) application on male BALB/c mice and IL‐17A intervention was performed by lateral ventricular catheterization." (PMID 39660880, 2024). "In the IMQ-induced psoriasiform dermatitis mouse model, FTY720 inhibited the migration of IL-17A-producing γδT cells from lymph nodes to the skin." (PMID 35741330, 2022). "Furthermore, PD-1 blockade-induced psoriasiform dermatitis is histologically characterized by prominent epidermal infiltration of CD8+ T cells and overexpression of IL-6, IL-23, and IL-17A cytokines." (PMID 40936709, 2025). "Reduction of Flii levels did not alter IL-23 and IL-17A cytokine levels as previously observed in psoriasiform dermatitis suggesting that Th17 responses are not involved in this model of AD." (PMID 30147695, 2018).
steatosis (31 papers, 2013 to 2025). Increased lipid within the cytoplasm of cells. "In clinical patients, the transition from steatosis to NASH has been demonstrated to be associated with hepatic infiltration of IL-17A-producing cells." (PMID 32929325, 2020). "Further, we show that deficiency of IL-17A, IL-17F or IL-17RA results in increased steatosis, but reduced steatohepatitis when fed MCDD." (PMID 26895034, 2016). "We observed that the frequency of IL-17A expressing cells positively correlated with both the level of steatosis and liver inflammation." (PMID 37774007, 2023). "Interleukin-17A (IL-17) is another pro-inflammatory cytokine that activates macrophages and regulates steatosis in the liver." (PMID 35269779, 2022). "The NAS result showed that the decreased total NAS was from the decreased score of inflammation other than steatosis and ballooning, supporting the anti-inflammatory effect of anti-IL-17A." (PMID 32929325, 2020). "In summary, we described a humanized mouse model for diet-induced NAFLD and showed that subsets of CD4+ T cells, specifically IL-17A-secreting Th17 and IFNγ -secreting Th1, play a key role in the progression of steatosis to fibrosis." (PMID 33013934, 2020). "In contrast, IL-17RA-/-, IL-17A-/-, and IL-17F-/- mice, despite increased steatosis, exhibited significant protection from hepatocellular damage compared to WT controls." (PMID 26895034, 2016). "Overall, IL-17A is a critical mediator of chronic liver injury, mediating the interaction between liver macrophages/Kupffer cells, HSCs, and steatotic hepatocytes and initiating the transition from simple steatosis to NASH." (PMID 38140293, 2023). "Regarding iNKT (NKTs with TCR composed by invariant αβ chains and specially enriched in the liver), the frequencies in peripheral blood of activated CXCR3+ IFN-γ+ T-bet+ and IL-17A+ iNKT cells were also increased in NASH patients in comparison with those with simple steatosis or healthy controls." (PMID 35052726, 2021). "Our study aims to investigate these issues by exploring the connections between IL-17A/F, TLR4, and inflammatory markers, as well as their associations with the severity of steatosis and the likelihood of fibrosis, to identify new biomarkers that could guide future therapeutic strategies." (PMID 39335657, 2024). "Among the cytokines tested, IL-17A had the greatest fold-increase in the peripheral blood of HIL mice on the HFHC diet and decreased significantly when these mice were depleted of CD4+ T cells, implying that IL-17A-producing Th17 CD4+ T cells may contribute to steatosis-to-fibrosis progression." (PMID 33013934, 2020). "An important role is played by IL-10/IL-17A and IL-10/IL-22 relations in the progression from simple MASLD steatosis to advanced MASLD inflammatory steatosis." (PMID 40918132, 2025). "In patients with mild/moderate steatosis, a significant positive correlation was observed between the SII and IL17A (r = 0.36, p = 0.010), the PIV and the CAR (r = 0.29, p = 0.011), the PIV and the SII (r = 0.87, p < 0.0001) and the PIV and IL17A (r = 0.3, p = 0.036)." (PMID 39335657, 2024). "The depletion of the Th17 cytokine IL-17A was also shown to be protective in the context of wild type mice fed a MASH-inducing diet, whereas the administration of recombinant IL-17A led to augmented hepatic damage, steatosis, injury, and fibrosis." (PMID 38892602, 2024). "Nevertheless, it is interesting to mention that IL-17A+ cells were absent in cases with mild steatosis with its consequent impact on the IL-17A+/Foxp3+ cell ratio." (PMID 33664397, 2021). "Most remarkable, only those severe cases displayed Foxp3+ and IL-17A+ cells; one possible explanation for this observation could be that CD4+ lymphocyte frequency is very low in steatosis grade 1 and 2 cases, therefore these subpopulations may be underrepresented in these stages." (PMID 33664397, 2021).
steatosis (continued). "However, in patients with mild/moderate steatosis, a significant positive correlation was observed between the SII and IL17A (r = 0.36, p = 0.010), the PIV and the CAR (r = 0.29, p = 0.011), the PIV and the SII (r = 0.87, p < 0.0001), and the PIV and IL17A (r = 0.3, p = 0.036)." (PMID 39335657, 2024).
autoimmune hepatitis (30 papers, 2011 to 2026). Hepatitis caused by autoantibodies. "For example, in experimental autoimmune hepatitis (AIH), antagomir-155 inhibited the differentiation of Th17/Treg by suppressing the secretion of IL-17A and IL-23, thereby alleviating the progression of AIH." (PMID 34147072, 2021). "Regarding IL-17A, elevations have been detected in HBV, HCV, autoimmune hepatitis and primary biliary cirrhosis in which an IL-17A response is suggested to be disadvantageous." (PMID 23372820, 2013).
autoimmune thyroid disease (30 papers, 2017 to 2025). Inflammatory disease of the thyroid gland due to autoimmune responses leading to lymphocytic infiltration of the gland. "A minor variant A allele of rs3819025 of the IL-17A gene protects against Graves’ disease, an autoimmune thyroid disease." (PMID 38139455, 2023). "IL-17A is also associated with thyroid autoimmunity during pregnancy." (PMID 32477272, 2020). "In this study, the expressions of IL-17A and downstream signaling were determined in rats with autoimmune thyroiditis." (PMID 35178026, 2021). "However, few studies have focused on the relationship between the IL-17A cytokine and thyroid status in pregnant women, excluding the effects of thyroid autoimmunity." (PMID 32477272, 2020). "Activated ERβ could directly bind to IL-17A and IL-21 gene promoters, and also indirectly promote IL-21 and RORγt gene transcription through interaction with NF-κB to stimulate the development of experimental autoimmune thyroiditis." (PMID 38730302, 2024). "Our objective was to investigate whether IL-17A is a risk factor for thyroid dysfunction in the absence of thyroid autoimmunity and levothyroxine interventions in China pregnant women." (PMID 32477272, 2020). "Diarylpropionitrile, a specific agonist of ERβ and not of ERα, in vivo enhanced IL-17A, IL-21, and RORγt mRNA levels in splenocytes of experimental autoimmune thyroiditis model mice through binding of the agonist-activated ERβ to IL-17A and IL-21 gene promoters." (PMID 31547021, 2019).
abscess (29 papers, 2010 to 2025). An inflammatory process characterized by the accumulation of pus within a newly formed tissue cavity which is the result of a bacterial, fungal, or parasitic infection or the presence of a foreign body. "Increased expression of mRNA encoding IL-17A and IL-17F was detected predominantly within macrophages in areas of dermal inflammation caused by intradermal injection of purified toxins or at the deep border of abscesses in those animals inoculated with either USA300 strain." (PMID 25719526, 2015). "In a murine model of intraperitoneal sepsis with abscess formation, an increase in the number of Th17 cells in the peritoneal cavity was observed, whereas the treatment with a neutralizing antibody against IL-17A prevented the abscesses formation." (PMID 36982834, 2023). "A previous study reported that CD4+ T cells mediated abscess formation in intra-abdominal sepsis in an IL-17A-dependent manner." (PMID 32849528, 2020). "Neutralization of IL-17A promoted resistance to intra-abdominal abscess formation in mice challenged with Bacteroides fragilis or abscess-inducing zwitterionic polysaccharides." (PMID 32849528, 2020). "For instance, IL-17A has been reported to be present in Hidradenitis suppurativa, a devastating neutrophil-rich inflammation with formation of nodules and abscesses." (PMID 32010143, 2019). "In psoriatic lesions, IL-17A, IL-17E, and IL-17F are involved in neutrophil accumulation, followed by the formation of epidermal micro abscesses." (PMID 32010143, 2019). "In one study, administration of neutralizing antibodies to IL-17A was correlated with decreased formation of intra-abdominal abscesses, decreased defense, and exacerbated systemic bacterial infections." (PMID 29590259, 2018). "Furthermore, neutralizing IL-17A in local S. aureus infection resulted in larger abscesses in the skin." (PMID 35446923, 2022). "IL-23 injection induced skin inflammation in the ears, as demonstrated by increased histology scores of multiple parameters (inflammation, abscesses, acanthosis, ulceration, parakeratosis), as well as mRNA expression levels of IL-17A, IL-17F, IL-22 and TNFα, compared with saline treated mice." (PMID 27905482, 2016). "Corresponding to this, protective efficacy NDV-3 induced increases in CD3+ T-cell and neutrophil infiltration, and IL-17A, IL-22, and host-defense peptide expression in local settings of SSSI abscesses." (PMID 25309545, 2014). "Higher expression levels of IFN-γ and IL-17A were found in stromal inflammatory cells from PDM patients with abscess formation than those without abscess formation." (PMID 28182101, 2017).
breast tumor (29 papers, 2008 to 2025). "IL-17A can stimulate breast tumorigenesis and, in turn, CAFs, γδT and breast tumor cells increase Th17 cell recruitment and IL-17A production." (PMID 36835413, 2023). "Another study demonstrated that an increased number of IL-17A-producing cells are found mainly in ER– and triple-negative/basal-like breast tumors." (PMID 35954312, 2022). "Our data strongly support the use of MDSC depletion therapy in treating IL-17A-expressing breast tumor patients." (PMID 32770025, 2020). "Recent research suggests that in the breast tumor environment, tumor-infiltrating T lymphocytes (TILs) secrete IL-17A, to activate the MAPK pathway, promoting proliferation and resistance to conventional chemotherapeutic agents." (PMID 24778632, 2014). "A transwell assay verified that rhIL-17A can promote the proliferation of THP-1, which means that IL-17A may promote the development of breast tumor cells through macrophage attraction." (PMID 39235230, 2024). "IL-17A’s role as a chemosensitive cytokine in TNBC may offer new opportunities for treating chemoresistant breast tumors and other cancer types." (PMID 35924165, 2022). "It has been reported that IL-17A enhances the phosphorylation of MEK–ERK in breast tumor cells." (PMID 27935862, 2017). "In breast tumors, IL-17A is associated with ER negative or triple negative tumors and poor prognosis." (PMID 28609459, 2017). "Interestingly, in contrast to IL-17A, which is produced by TILs, the main source of IL-17B in breast tumors seems to be tumor cells themselves and potentially fibroblasts, but not TILs." (PMID 29371916, 2017). "In breast tumour, just like its counterpart in the blood, the CCR6 defines an IL17A producer and the CD16 subtype is an IFNγ producer with high cytotoxic potential." (PMID 33268347, 2021).
diabetic nephropathy (29 papers, 2015 to 2025). "Although little is known about the potential effect of IL-17 on glomerular basement membrane (GBM), the IL 17 presence was associated with GBM thickening in a model of accelerated diabetic nephropathy; while IL-17A blockade with antibody reduced this effect." (PMID 34540858, 2021). "Previous studies implicated that the RORγt/IL-17A axis played a pivotal role in the onset and progression of diabetic nephropathy." (PMID 32429598, 2020). "Therefore, we investigated examined the role of IL-17A in autophagic response of mice with STZ-induced diabetic nephropathy and genetically deficient in IL-17A." (PMID 33691614, 2021). "In accelerated models of diabetic nephropathy, the presence of IL-17 correlates with glomerular basement membrane thickening, and the inhibition of IL-17A with antibodies mitigates this effect." (PMID 40977724, 2025). "As has been observed in a model of diabetic nephropathy, an IL-17 neutralizing antibody (IL-17A) improved kidney lesions and disease progression." (PMID 37298378, 2023). "In kidney biopsy samples of T2D patients with diabetic nephropathy CD4+ IL-17+ T cells were found, and IL-17A was the key cytokine produced by these cells." (PMID 32961903, 2020). "Here, we review current knowledge regarding the involvement of Th17/IL-17A in the genesis of diabetic renal injury, as well as the rationale behind targeting IL-17A as an additional therapy in patients with diabetic nephropathy." (PMID 31963845, 2020). "Furthermore, recent studies have demonstrated that IL‐17A blockade can significantly reduce albuminuria and kidney injury in mouse models of diabetic nephropathy, reinforcing its potential as a therapeutic target." (PMID 39946217, 2025). "Here, we provide further insights into the role of IL-17A in diabetic kidney disease." (PMID 33691614, 2021). "The role of IL-17A in the pathogenesis of diabetic nephropathy requires further research." (PMID 32961903, 2020). "Notably, the cytokine IL17 has a differentiated function in diabetic kidney disease: Ablation of intrarenal Th17 cells ameliorated early diabetic nephropathy, while the administration of low-dose IL17A had beneficial effects." (PMID 31052201, 2019). "More recently, preclinical and clinical studies have shown the involvement of IL-17A in nonimmune nephropathies, including hypertensive and diabetic nephropathy." (PMID 32987705, 2020).
heart failure (29 papers, 2013 to 2026). Inability of the heart to pump blood at an adequate rate to meet tissue metabolic requirements. "More in-depth longitudinal or experimental research is necessary to determine whether IL-17A directly contributes to reduced EF or merely serves as a marker of systemic inflammation associated with heart failure." (PMID 40599146, 2025). "In male mice with transverse aortic constriction (a LV pressure overload model), IL-17a circulatory and myocardial levels were increased, linking this interleukin to the development of heart failure." (PMID 40558497, 2025). "Furthermore, increased Th17 cells are correlated with heart failure, and biopsies with detectable IL-17A+ cells show greater fibrosis." (PMID 32269577, 2020). "We demonstrated that plasma IL-17A levels has an accurate sensitivity and specificity to predict heart failure in serology-positive patients and might be a useful parameter to distinguish patients with or without cardiac impairment." (PMID 28278264, 2017). "We demonstrated that plasma IL-17A levels has an accurate sensitivity and specificity to predict heart failure in serology-positive patients and might be a useful parameter to distinguish patients with or without cardiac impairment, as CARD and IND patients, respectively." (PMID 28278264, 2017). "However, a recent study investigating the role of IL-17A in non-chagasic inflammatory dilalated cardiomyopathy–an important cause of noncongenital heart failure in individuals under the age of 40, has reported that IL-17A/IL-17RA signaling pathway is required for the development of the disease." (PMID 28278264, 2017). "The contribution of IL-17A levels to discriminate diseased cases with heart failure (CARD) from infected patients without cardiac impairment (IND) is shown in the ROC curve." (PMID 28278264, 2017).
Parkinson disease (29 papers, 2018 to 2026). A progressive degenerative disorder of the central nervous system characterized by loss of dopamine producing neurons in the substantia nigra and the presence of Lewy bodies in the substantia nigra and locus coeruleus. "It has been reported that IL-17A exacerbates dopaminergic neuronal loss only in the presence of microglia and IL-17A-treated microglial medium facilitates dopaminergic neuronal death, suggesting that IL-17A accelerates neurodegeneration in Parkinson’s disease depending on microglial activation." (PMID 34750361, 2021). "Patients with Parkinson’s disease had elevated frequencies of Th1 cells and serum levels of IL10 and IL17A as compared to healthy controls." (PMID 36038917, 2022). "In patients with Parkinson’s Disease, rTMS reduced plasma pro-inflammatory cytokines INF-y and IL-17a." (PMID 33571313, 2021).